IL4 (interleukin 4)
Diseases named in the same sentence as IL4 in open-access papers (continued):
Sharing a sentence is not in itself a finding about the gene and the disease.
atopic dermatitis (397 papers, 1993 to 2026). "This skin disease is associated with atopic dermatitis and has been shown to improve with the treatment of dupilumab, an inhibitor of the IL-4 and IL-13 immune pathway." (PMID 40861695, 2025). "It is well established that atopic dermatitis is associated with the excessive secretion of IL-4 and IL-10 by Th2 cells, leading to the unstable production of IL-12 and the reduced secretion of IFN-γ." (PMID 40299438, 2025). "Psoriasis is a disease primarily driven by Th17 T-cells and associated IL-17 activation, whereas atopic dermatitis (AD) is characterized by a strong Th2 response with overproduction of IL-4 and IL-13." (PMID 41517378, 2025). "Various polymorphisms in the genes encoding IL-4, IL-13, and their receptors have been associated with a genetic predisposition to atopic dermatitis in both children and adults." (PMID 41002407, 2025). "To mimic skin barrier dysfunction, we treated keratinocytes and full-thickness skin equivalents with IL-4 and IL-13, cytokines that are implicated in atopic dermatitis, and confirmed the downregulation of tight junction and differentiation markers." (PMID 39329899, 2024). "Our findings suggest a potential role for IL-4 and IL-1RA in the risk of developing atopic dermatitis according to the IVW method." (PMID 38357652, 2024). "It has been reported that the specific diagnostic cytokines of atopic dermatitis are IL‐4 and IL‐13." (PMID 38648253, 2024). "Atopic dermatitis is a common inflammatory skin disease related to the underlying dysregulation of T helper 2 (Th2) cells and overexpression of interleukin (IL)-4." (PMID 39360077, 2024). "The results showed that in clinical practice, IL-4 and IL-1RA were suggestive indicators of atopic dermatitis risk (OR = 0.878, 95% CI = 0.78–0.99, p = 0.036; OR = 0.902, 95% CI = 0.82–1.00, p = 0.045)." (PMID 38357652, 2024). "Th2 polarization facilitates S. aureus binding and colonization, and IL-4 and IL-13 inhibit skin production of AMPs, predisposing atopic dermatitis skin to S. aureus infections, which, in turn, further exacerbates skin inflammation and barrier defects." (PMID 39202657, 2024). "The significant positive correlations between IgE and IL‐4 and IL‐13 indicate that the immunologic response to type I hypersensitivity reaction in atopic dermatitis is caused by environmental allergens in dogs by increasing IgE, IL‐4 and IL‐13 production." (PMID 38648253, 2024). "The present finding was also in agreement with Chan (2018) that the specific diagnostic cytokines of atopic dermatitis are IL‐4 and IL‐13." (PMID 38648253, 2024). "In terms of atopic dermatitis, a predominant Th2 response in the acute phase causes recruitment of IL-4, 5, 13, and 31, which promotes local inflammation." (PMID 39360077, 2024). "For instance, IL-4 and IL-13, pathogenic for atopic dermatitis, and IL-17A, pathogenic for psoriasis, lead to a downregulation of filaggrin." (PMID 38132754, 2023). "The presence of IL-4 and IL-13 in skin lesions of atopic dermatitis is associated with the stimulation of thymic stromal lymphopoietin (TSLP) production in keratinocytes upon exposure to external substances." (PMID 37630370, 2023). "Atopic dermatitis, in contrast, is believed to be mediated by Th2 and Th22, and the associated secretion of IL-4/IL-13 and IL-22, respectively." (PMID 37138890, 2023). "Interleukin-4 polymorphism is widely correlated with rheumatoid arthritis/atopic dermatitis/allergic rhinitis and other diseases." (PMID 36600245, 2023). "The type 2 cytokines interleukins (IL)-4, IL-13, and IL-33 are central in the inflammatory pathogenesis of atopic dermatitis and implicated to play an additional role in itch sensation in murine models." (PMID 37868811, 2023). "Cytokines such as Thymic Stromal Lymphopoietin (TSLP), Interleukin-33 (IL-33), and Interleukin-4 (IL-4) are commonly expressed in atopic dermatitis and play roles in causing skin itching." (PMID 37762597, 2023).
atopic dermatitis (continued). "Psoriasis is mainly driven by Th17 cells and IL-17, whereas atopic dermatitis is linked to Th2-associated inflammation, IL-4 and IL-13." (PMID 36937045, 2023). "S14 also reduced the Th2 response in a mouse model of atopic dermatitis, with a decrease in the IL-4 expression associated with increased IL-12." (PMID 38067173, 2023). "Humanized antibodies against IL-13, IL-4, and IL-31 proved effective in treatment of itch-associated atopic dermatitis but remain to be validated in chronic itch." (PMID 36077340, 2022). "The onset of atopic dermatitis is due to an antigen disturbing the balance of Th1/Th2 cytokines to cause overproduction of Th2 cytokines such as IL-4, IL-5, and IL-13, while stimulating the B cells to increase the serum IgE level." (PMID 35694270, 2022). "For instance, the expression of filaggrin is downregulated by the interleukins IL-4 and IL-13, which are pathogenic for atopic dermatitis, as well as by IL-17A, which is pathogenic for psoriasis." (PMID 36362566, 2022). "In various adult studies, vitD has been shown to inhibit and stimulate IL-4 activation in various immune responses and has been investigated as a treatment for IL-13-associated atopic dermatitis." (PMID 35334923, 2022). "Considering the pathogenic role of IL-4 in AD (and in other allergic dermatitis), IL-4 signaling is regarded as a promising potential therapeutic target for the treatment of AD." (PMID 34577127, 2021). "Atopic dermatitis has a strong Th2 component associated with IL-4 and IL-13 over-production by Th2-polarized lymphocytes in the acute phase of the disease." (PMID 33806193, 2021). "Atopic dermatitis is associated with T-cells exhibiting a Th2 polarized phenotype, with increased expression of Th2 cytokines, such as IL4, Il5, and IL13." (PMID 34445339, 2021). "The underlying pathology of atopic dermatitis revolves mainly around type 2 immune-mediated reaction, with cytokines interleukin-4 (IL-4) and interleukin-13 (IL-13) playing a key role in its pathogenesis." (PMID 32382467, 2020). "Psoriasis is a disease driven by Th17 cells associated with IL-17 activation, while atopic dermatitis has a strong Th2 component associated with IL-4 and IL-13 overproduction." (PMID 32873845, 2020). "Recently, IL-31 and IL-4 have been implicated in intractable itch associated with atopic dermatitis." (PMID 32152328, 2020). "Atopic dermatitis has also been linked to variants within the genes encoding the T2 pathway-associated cytokines/cytokine receptors IL-4, IL-13, IL-4RA, and IL-31 and associated downstream molecules like STAT6 and GATA3." (PMID 31028434, 2019). "Reduced inflammation was confirmed histologically and by reduced concentrations of cytokines, which are frequently associated with atopic dermatitis (IL-4, IL-13, TARC) and cytokines for which a major role in the mediation of itch has been described (TSLP)." (PMID 29970189, 2018). "Here, we show that cytokine IL-4 which is implicated in the development of chronic inflammatory disease atopic dermatitis (AD) induces expression of transcription factor FoxQ1 in human monocytes and macrophages." (PMID 29203829, 2017). "Compared with extrinsic atopic dermatitis, the intrinsic form is associated with less IL-4 and IL-13 production." (PMID 28216598, 2017). "Application of dTBP2 inhibited the mRNAs levels of proinflammatory cytokines such as IL-6 well as Th2-related cytokines/chemokines associated with pathogenesis of atopic dermatitis including IL-4, IL-5, IL-13, TSLP, MCD, and TARC." (PMID 28134765, 2017). "Recently, resveratrol was shown to effectively reduce the expression of HMGB1, RAGE, and various cytokines, including TNF-α and IL-4, in inflamed skin caused by atopic dermatitis." (PMID 26950148, 2016). "For example, in patients with atopic dermatitis, acute lesions are associated with increased IL-4 mRNA with lymphocytic infiltration, whereas chronic lesions have a predominance of IL-5 mRNA with eosinophil infiltration." (PMID 24971469, 2014).
atopic dermatitis (continued). "Several markers are employed to measure the severity of clinical symptoms of experimental atopic dermatitis including degree of scratching, pruritic skin lesion, and levels of pathogenic cytokines including IL-4, IL-5, IL-13 and IFN-γ." (PMID 24499290, 2013). "In a previous survey by Nuttall and colleagues, canine atopic dermatitis was associated with overexpression of IL-4 mRNA and reduced transcription of TGF-β compared to healthy skin." (PMID 22536131, 2012). "Atopic dermatitis has been associated with the Th2 phenotype and dominance of IL-4, IL-5, and IL-13 secretion." (PMID 21303540, 2011). "Previous studies on atopic dermatitis suggest that skin lesions accompanied by topical eosinophilia and systemic IgE elevation are associated with Th2 cytokines (IL-4, IL-5, and IL-13)." (PMID 21197410, 2010). "The increase of IL-4 caused by the challenge was comparable to the one obtained in lymphocytes from atopic dermatitis patients stimulated with anti-CD3 antibodies." (PMID 20011655, 2009). "Additionally, reports have linked nemolizumab to exacerbations of atopic dermatitis (AD), BP, and urticaria - conditions primarily driven by Th2 cytokines such as IL-4, IL-5, and IL-13." (PMID 40104458, 2025). "Recent findings suggest that IL-4 and IL-13 play an important role in the downregulation of inflammatory processes underlying atopic dermatitis pathology and may favorably regulate the disease course." (PMID 38921035, 2024). "IL-4 and IL-1RA may have inhibitory roles in the risk of developing atopic dermatitis, while SCGF-b may have a promoting role in the risk of developing psoriasis." (PMID 38357652, 2024). "Atopic dermatitis is caused by chronic inflammation of the skin tissue, and the onset of atopic dermatitis is closely related to various inflammatory mediators such as IL-4, IL-13, CCL5, CCL17, and CCL22." (PMID 39599592, 2024). "By using the IVW method, we found that higher levels of IL-4 and IL-1RA genetic prediction were associated with a lower risk of atopic dermatitis, OR = 0.878, 95% CI = 0.78–0.99, p = 0.036 per 1 standard deviation (SD); OR = 0.902, 95% CI = 0.82–1.00, p = 0.045 per 1 standard deviation (SD)." (PMID 38357652, 2024). "The extract also reduced the expressions of cytokines such as TSLP, IL-33, and IL-4, which are commonly expressed in atopic dermatitis and play roles in causing skin itching, suggesting that the extract may have had a notable effect on reducing itching." (PMID 37762597, 2023). "Dupilumab is currently used in atopic dermatitis both for its IL-4 and IL-13 effects and could be tested in association with antiparasitic drugs." (PMID 37575260, 2023). "The interleukins IL-4 and IL-13 reduce the expression of filaggrin and weaken the permeability barrier of keratinocytes; these effects might be responsible for the pathogenic actions of IL-4 and IL-13 in atopic dermatitis." (PMID 36362566, 2022). "Furthermore, in patients with atopic dermatitis, elevated IL-4 and IL-31 levels stimulate sensory nerves and cause itching." (PMID 34959939, 2021). "Furthermore, IL-4 is generally associated with atopic diseases (e.g., allergic rhinitis and atopic dermatitis)." (PMID 35387066, 2021). "Sixth, one meta-analysis reported that the − 590 C/T polymorphism within the IL-4 (interleukin-4) gene may be linked to the risk of atopic dermatitis, especially for Asian children." (PMID 31101031, 2019). "Chronic ILC2 activation was reported to contribute to a large variety of tissue inflammatory disorders such as asthma in the lung and atopic dermatitis in the skin, which are generally associated with over-production of the type 2 inflammatory cytokines such as IL-4, IL-5, and IL-13." (PMID 28271445, 2017). "It has been suggested that the increased expression of IL-4 and IL-13 in atopic dermatitis skin may explain the susceptibility to bacterial and viral skin infections by reducing antimicrobial peptide expression." (PMID 23193414, 2012).
atopic dermatitis (continued). "Notably, dupilumab’s mechanism of action overlaps with the inflammatory pathways involved in atopic comorbidities, such as atopic dermatitis, allergic rhinitis, and chronic rhinosinusitis with nasal polyps, all of which are associated with elevated levels of IL-4 and IL-13 cytokines." (PMID 40843371, 2025). "The association that GD has with atopic dermatitis has raised suspicion of a potential immune-mediated pathogenesis, and has consequently encouraged some clinicians to treat refractory GD with immune-modulators like dupilumab, an interleukin (IL)-4 and IL-13 inhibitor." (PMID 40861695, 2025). "Furthermore, while it is noteworthy that higher IL-4 levels in our study were associated with a lower risk of atopic dermatitis, several studies have demonstrated the involvement of IL-4 in the onset and development of atopic dermatitis." (PMID 38357652, 2024). "As previously reported, the increase in serum IL‐4 and IL‐13 concentrations in dogs with atopic dermatitis in this study may indicate that the cytokine response to allergens in atopic dermatitis caused by environmental allergens in dogs is mainly mediated by IL‐4 and IL‐13." (PMID 38648253, 2024). "We included adults (aged over 18 years) with an ICD‐10 code for atopic dermatitis who initiated treatment with either a JAKi (tofacitinib, upadacitinib, and abrocitinib) or an IL‐4/‐13i (dupilumab, lebrikizumab, and tralokinumab)." (PMID 40293104, 2026). "Chronic Th2-skewed inflammation in atopic dermatitis, characterized by sustained IL-4, IL-13, and IL-6 signaling, can disrupt the BBB, promote microglial activation, and induce neuroinflammatory cascades that impair Aβ clearance." (PMID 41465136, 2025). "Dupilumab, an IL-4 and IL-13 receptor antagonist, has demonstrated efficacy in controlling severe, recalcitrant atopic dermatitis by mitigating T helper 2-driven inflammation." (PMID 39777027, 2025). "Atopic dermatitis (AD) is a chronic inflammatory skin disease characterized by epidermal barrier dysfunction and immune dysregulation, with interleukin (IL)-4, IL-13, and IL-31 recognized as key mediators." (PMID 40364058, 2025). "IL-4 and IL-13 are type 2 cytokines involved not only in the inflammatory pathways of atopic dermatitis but also in regulating the tumor microenvironment." (PMID 40981274, 2025). "Background/Objectives: Dupilumab is an interlekin-4 receptor antibody that exerts its efficacy by inhibiting the signaling pathway of interleukin-4/interleukin-13, and it is currently used clinically as a highly potent therapeutic for atopic dermatitis." (PMID 39997051, 2025). "Atopic dermatitis (AD) is a chronic inflammatory skin disease primarily treated with corticosteroids and dupilumab, a monoclonal antibody targeting interleukin (IL)-4 and IL-13." (PMID 40999478, 2025). "- Atopic dermatitis is primarily Th2-driven, characterized by IL-4, IL-13, TSLP, and IL-33, promoting eosinophil and mast cell infiltration." (PMID 41479908, 2025). "Dupilumab is a human monoclonal antibody targeting the Th2 immune axis by inhibiting IL-4 and IL-13 and has shown efficacy for moderate to severe atopic dermatitis and sporadic cases of NE in adults." (PMID 40264610, 2025). "In IL-4-stimulated keratinocytes, which mimic Th2-driven inflammation in atopic dermatitis, brief submicromolar pretreatment reduced TSLP expression at both mRNA and protein levels." (PMID 41304852, 2025). "Treatment with β-sitosterol resulted in a reduction in the amount of inflammation-related mRNA and protein in atopic dermatitis lesions and in the levels of histamine, IgE, and interleukin-4 in the serum." (PMID 40141186, 2025). "Therapies targeting the cytokines IL-4 and IL-13, key mediators of the Th2-dependent immune pathway, play a crucial role in the treatment of atopic dermatitis." (PMID 41002407, 2025). "Atopic dermatitis is characterized by disrupted skin barrier function and elevated levels of pro‐inflammatory cytokines, such as IL‐4, IL‐5, and IL‐13." (PMID 40536117, 2025).
atopic dermatitis (continued). "In atopic dermatitis, chronic elevation of cytokines such as IL-4, IL-13, and IL-6 perpetuates a Th2-skewed immune response that extends beyond the skin, leading to persistent systemic inflammation." (PMID 41465136, 2025). "Interleukins IL-4, Il-5, IL-10, IL-13 and IL-33 play an important role in atopic dermatitis patients." (PMID 40771803, 2025). "Dupilumab, a human monoclonal antibody that targets both IL-4 and IL-13, has shown efficacy for moderate to severe atopic dermatitis and other immune-mediated disorders." (PMID 40264610, 2025). "Central mediators of this axis include IL-4, IL-13, and IL-31, which play crucial roles in driving inflammation in atopic dermatitis." (PMID 41002407, 2025). "MIT also presents TRPA1 mediated effects in vivo as MIT‐induced paw edema and IL‐4 expression in MIT‐induced allergic dermatitis were downregulated in TRPA1‐defcient mice." (PMID 40329600, 2025). "Our findings in the goat AD model demonstrate a Th2-dominant immune response, with elevated IL-4 and IL-13 cytokine expression, which closely mirrors observations in human and murine models of atopic dermatitis." (PMID 39943182, 2025). "Although both TH2 cells and group 2 innate lymphoid cells are considered as the primary cellular sources of IL-4 and IL-13 in atopic dermatitis skin, mast cells also contribute to the elevated levels of these TH2 cytokines." (PMID 39890627, 2025). "The late-stage atopic dermatitis–asthmatic pattern is defined as immune dysregulation driven by Th2 cells, characterized by elevated levels of interleukin (IL)-4, IL-13, and IL-5." (PMID 41155390, 2025). "Dupilumab, a monoclonal antibody that targets interleukin-4 and interleukin-13, is one of the approved biologic treatments for moderate-to-severe atopic dermatitis." (PMID 39906475, 2025). "Atopic dermatitis is characterized by the release of T-helper 2 (Th2) cytokines IL-4 and IL-13 and T-helper 17 (Th17) cytokines IL-17, IL-22, and interferon (IFN)-γ (chronic eczema)." (PMID 39062477, 2024). "In the initial and acute phase of Atopic Dermatitis (AD), a Th2-based immune response (IL-4, IL-13, thymic stromal lymphopoietin, and eosinophils) is typically observed." (PMID 39119011, 2024). "Clinical intake of DS has been reported to improve allergic skin responses by restoring mineral imbalances in atopic eczema/dermatitis syndrome, and by reducing levels of IgE and Th2 cytokines (IL4, IL6, and IL13) in allergic rhinitis." (PMID 38921545, 2024). "It inhibits the signaling of IL-4 and IL-13, which drive inflammatory skin conditions, like atopic dermatitis." (PMID 39507480, 2024). "In the context of eczematous dermatitis, the inflammatory milieu is often dominated by a Th2‐driven immune response, characterized by cytokines such as IL‐4, IL‐5, and IL‐13." (PMID 39670074, 2024). "Among the innovative medicines for atopic dermatitis (AD), dupilumab is a completely human antibody that identifies IL-4Rα and inhibits the signaling pathways of both IL-4 and IL-13 receptors." (PMID 39119011, 2024). "Pearson correlation analysis between serum IAP, I‐FABP, TFF‐3, IgE, IL‐4, IL‐13, monocyte and eosinophil parameters in dogs with atopic dermatitis." (PMID 38648253, 2024). "Serum concentrations of IAP (p < 0.01), TFF‐3 (p < 0.01), IgE (p < 0.01), IL‐4 (p < 0.01) and IL‐13 (p < 0.01) were significantly higher in dogs with atopic dermatitis, compared to the healthy ones." (PMID 38648253, 2024). "The role of these cytokines in the pathophysiology of atopic dermatitis is supported by the response to dupilumab, which interrupts IL-4 signalling, and Janus kinase (JAK) inhibitors, which result in the inhibition of IL-4 receptors." (PMID 38731996, 2024). "To further investigate the function of dhAvD in the whole skin model, we used a reconstructed human skin model (RHS) treated with IL-4 and IL-13, which are known to induce atopic dermatitis-like conditions." (PMID 39329899, 2024).